CTSK (cathepsin K)
Diseases named in the same sentence as CTSK in open-access papers (continued):
Sharing a sentence is not in itself a finding about the gene and the disease.
periodontitis (continued). "Results with CTSK responses showed a similar prevalence of positive correlations in healthy and periodontitis tissues, while a cluster of genes were negatively correlated with CTSK primarily in the periodontitis tissues." (PMID 27486459, 2016). "Our analysis of single-cell RNA sequencing and RNA sequencing data from gingival tissues of mice and humans with periodontitis revealed high expression of CTSK in fibroblasts, further supporting its critical role in the degradation of gingival connective tissue." (PMID 40315697, 2025). "Given the specific high expression of CTSK in fibroblasts during the early stages of periodontitis, we hypothesize that gingival recession during OTM may also be closely associated with the upregulation of CTSK." (PMID 40315697, 2025). "Moreover, although the number of fibroblasts in periodontitis gingival tissue was reduced compared to healthy tissue, the proportion of CTSK-positive fibroblasts increased." (PMID 40315697, 2025). "GCF from patients with periodontitis had a higher cathepsin-K level." (PMID 38420070, 2024). "Cathepsin K is a key modulator of periodontitis-induced bone destruction and may be involved in the immune regulation of periodontitis via the TLR9 signaling pathway." (PMID 37334378, 2023). "Furthermore, cathepsin K inhibitors (Ctsk-inhibitors) can stop the destructive process found in the periodontitis." (PMID 36135916, 2022). "Meanwhile, we found both TC-ODN and ODN could decrease the inflammatory score in periodontitis rats, which was consistent with the immunoregulatory effect of CTSK." (PMID 36386169, 2022). "In addition, the expression of CTSK in gingival crevicular fluid is positively correlated with the severity of periodontitis, suggesting a stimulatory effect of CTSK on the progression of PDs." (PMID 33445732, 2021). "The increased concentration of CTSK in GCF was positively correlated with periodontitis." (PMID 33445732, 2021). "As expected, RA can promote the expression of CTSK in periodontitis lesions." (PMID 31737959, 2020). "Compounds that inhibit cathepsin K activity could be potential drugs to be further explored in the treatment or prevention of periodontitis." (PMID 29163477, 2017). "An intriguing example could be the lessons learned from the periodontitis resistant Cathepsin K knockout mouse." (PMID 29163477, 2017). "Cathepsin K deficiency was protective against both diseases, and the authors attribute that to the dampened inflammatory reactivity, with less TLR expression, less dendritic cells and less cytokines produced in the arthritis and periodontitis lesions." (PMID 29163477, 2017). "Furthermore, CtsK has been shown to be an efficient therapeutic strategy in preclinical studies, including inflammatory, metabolic, and autoimmune diseases, such as high fat acid-induced obese mice, experimental periodontitis, and collagen-induced arthritis (CIA)." (PMID 35547360, 2022). "We aimed to explore a novel target, cathepsin K (Ctsk)‐mediated TLR9‐related autophagy, during the progress of periodontitis with RA." (PMID 31737959, 2020). "CTSS is closely related to cathepsin K (CTSK), which has been shown to be upregulated in periodontitis." (PMID 29362520, 2017). "Furthermore, osteoclast activity was greatly enhanced by both F. nucleatum and its OMVs (middle row), and the expression of osteoclast markers, CTSK and DCST1, was increased by both F. nucleatum and its OMVs in rat periodontitis (lower two rows)." (PMID 39475060, 2024). "Moreover, except for strongly expressing by osteoclasts and specifically induced during osteoclast differentiation in general, CTSK was also found to contribute to the destruction of bone and the PDL in periodontitis based on its role in collagen degradation." (PMID 31907038, 2020). "The results showed that the gene expressions of bone erosion makers TRAP and cathepsin K were significantly increased in the ligature-induced periodontitis, rather than bone formation markers OC and ALP." (PMID 31886238, 2019).
periodontitis (continued). "Cluster 8 genes (n = 18) were similar to cluster 7 with negative correlations to MMP2 and CTSK in periodontitis and health, as well as negative correlations with MMP9 in periodontitis tissues." (PMID 27486459, 2016). "Cluster 7 grouped 28 genes with positive correlations to RANKL only in periodontitis tissues, and strong negative correlations to CTSK in periodontitis and MMP2 in both healthy and periodontitis samples." (PMID 27486459, 2016). "Cluster 6 contained 34 genes with strong positive correlations with MMP9 and CTSK in both healthy and periodontitis tissues, and a negative correlation with TNFα in periodontitis." (PMID 27486459, 2016). "Another study suggests that cathepsin K (Ctsk) influences the infiltration of dendritic cells and T cells, as well as the production of inflammatory factors through the TLR9 signaling pathway, serving as a key pathological regulator in both RA and periodontitis." (PMID 39811802, 2025). "In this study, we observed the non-osteoclastic upregulation of CTSK in periodontitis patients." (PMID 33445732, 2021). "The presence of Porphyromonas gingivalis can increase the RANKL/OPG ratio at periodontitis sites (Belibasakis, Meier, Guggenheim, & Bostanci, 2011; Sakellari, Menti, & Konstantinidis, 2008), and a high RANKL/OPG ratio can facilitate inorganic matrix dissolution by cathepsin‐K and metalloprotease." (PMID 31944625, 2019). "Moreover, the same study evidenced that lack of cathepsin K inhibited the expression of toll-like receptors 4, 5, and 9 and their downstream cytokine signaling in the gingival epithelial cell, indicating that the innate immune response was abrogated in periodontitis." (PMID 35547360, 2022). "Finally, genotypes are described that protect the mice from periodontitis: the SCID mouse, and mice lacking Tlr2/Tlr4, the Ccr1/Ccr5, the Tnf-α receptor p55, and Cathepsin K by attenuating the inflammatory reaction and the osteoclastogenic response." (PMID 29163477, 2017).
osteopetrosis (26 papers, 2009 to 2025). Osteopetrosis, also known as marble bone disease, is a descriptive term that refers to a group of rare, heritable disorders of the skeleton characterized by increased bone density on radiographs. "We also found one child with a clinical phenotype of osteopetrosis but homozygous variants in CTSK gene." (PMID 34777883, 2021). "Recently variants in the CTSK gene have also been reported in patients with intermediate osteopetrosis." (PMID 34777883, 2021). "Cathepsin K-deficient mice were shown to cause the hypermineralization of the long bone and growth plates and develop osteopetrosis." (PMID 32210820, 2020). "Cathepsin K knockout mice were shown to develop osteopetrosis caused by impaired osteoclastic bone resorption, and these results confirmed the role of these proteases in bone degradation processes." (PMID 22666151, 2012). "Interestingly, variants in CTSK have been identified in early onset osteopetrosis in a previous study." (PMID 34777883, 2021). "In mice, Ctsk knockout led to osteopetrosis and development of pycnodysostosis characteristics by decreasing osteoclastic resorptive activity and impairing CTSK secretion, which impeded bone organic matrix degradation and osteoclasts." (PMID 36077242, 2022). "Cathepsin K knockout mice experienced osteopetrosis (a congenital disorder in which the bones become overly dense) with severe loss in osteoclast activity." (PMID 25010555, 2014). "Cathepsin K knockout mice develop osteopetrosis because of the impaired matrix degradation; MMP-9 knockout mice show only transient disturbances in bone development." (PMID 23536866, 2013). "Inhibition of cathepsin K prevents matrix degradation, and deletion of the cathepsin K gene in mice leads to osteopetrosis." (PMID 19232111, 2009). "Likewise, cathepsin K knock-out (KO) mice develop osteopetrosis." (PMID 35478968, 2022). "Disruption of the cathepsin K and TRAP gene have been shown to lead to osteopetrosis (a congenital disorder characterized by overly dense bones)." (PMID 26516894, 2015). "If an osteoclast lacks a ruffled border and/or cathepsin K, bone resorption does also not occur, a condition known as osteopetrosis." (PMID 26426806, 2015). "In addition, absence of cathepsin K in humans leads to pycnodysostosis, a heritable disease characterized by osteopetrosis and a short stature." (PMID 35478968, 2022).
osteoarthritis (25 papers, 2005 to 2025). A noninflammatory degenerative joint disease occurring chiefly in older persons, characterized by degeneration of the articular cartilage, hypertrophy of bone at the margins and changes in the synovial membrane. "Previous work by others has shown that inhibition of cathepsin K activity reduces osteoarthritis-associated nociception in joints." (PMID 35501334, 2022). "Other pathological conditions with similar causes are osteoarthritis and rheumatoid arthritis, where cathepsin K degrades collagen II from the N-terminus, which leads to cartilage erosion." (PMID 30897858, 2019). "The methodology was based on a search in Pubmed and Pubchem by using keywords, including cathepsin K, chondrocyte, osteoarthritis, extracellular matrix, and cathepsin K inhibitors." (PMID 40243480, 2025). "Further, Ctsk deletion in a murine surgical osteoarthritis model (destabilization of the medial meniscus) protected against disease progression, as did pharmacological treatment with a cathepsin K inhibitor (SB-553484) in a canine model." (PMID 38144567, 2023). "Previously, another cathepsin K inhibitor L-006235 was reported to have a similar effect in MIA- (monosodium iodoacetate-) induced model of painful osteoarthritis." (PMID 35501334, 2022). "Studies also show inhibition of cathepsin K by betaine-attenuated osteoarthritis, since this cathepsin is involved in bone resorption and osteoclastogenesis." (PMID 36286438, 2022). "Cathepsin K is a protease known to be involved in not only bone remodeling and resorption, but also articular cartilage degradation that leads to osteoarthritis (OA)." (PMID 31937805, 2020). "The mounting evidence that osteoclasts play an important role in osteoarthritis (OA) pain lead us to investigate the effects of L-006235, a potent and selective inhibitor of cathepsin K, on pain behaviour and joint pathology in a model of OA pain." (PMID 30706033, 2018). "Nevertheless, the real impact of osteoblast cathepsin K synthesis in osteoarthritis remains to be investigated." (PMID 28425564, 2017). "In a destabilization-induced mice osteoarthritis model, cathepsin K gene knockout resulted in a delay in cartilage degradation." (PMID 26949397, 2016). "Cathepsin K (catK) expression is increased in cartilage, bone and synovium during osteoarthritis (OA)." (PMID 25592743, 2015). "The intra-helical cleavage of type II collagen by proteases, including collagenases and cathepsin K, is increased with aging and osteoarthritis (OA) in cartilage as determined by immunochemical assays." (PMID 22584047, 2012). "In analysis of this model, transgenic animals showed osteoarthritis and increased levels of cathepsin K with aging." (PMID 21880134, 2011). "Moreover, the low pH, as observed in advanced osteoarthritis, favors cathepsin K as a major collagenase in these diseases." (PMID 30897858, 2019). "Moreover, lysosomal cathepsins have been reported to play a key role in osteoarthritis pathogenesis and, in particular, cathepsin K has been found highly expressed in osteoarthritis." (PMID 28425564, 2017). "Thus, only one cathepsin K inhibitor MIV-711 (Medivir) are currently advanced into phase II trials for the treatment of osteoarthritis." (PMID 27999266, 2016). "In addition to the well-accepted role of matrix metalloproteinase collagenases in this process, immunohistochemical staining of cartilage from osteoarthritis patients, together with previous immunoassay data demonstrates the role for cathepsin K in this process." (PMID 22584047, 2012). "Links between cathepsin K and the pathophysiology of osteoarthritis (OA) can be established, not least because of the overabundance of cathepsin K in the serum of OA patients and the upregulation of cathepsin K in degraded cartilage in animal models of OA." (PMID 40243480, 2025). "For instance, in a guinea pig model for osteoarthritis in knees, prolonged cathepsin K inhibition reduced joint nociception." (PMID 35501334, 2022).
osteoarthritis (continued). "In addition, cathepsin K can cleave the proteoglycan aggrecan, which is also cleaved by cathepsins B, L, and S, and ECM bone protein osteonectin, further supporting its crucial role in osteoarthritis." (PMID 30897858, 2019).
Arthritis (23 papers, 2005 to 2025). Inflammation of a joint. "Cathepsin K, one of the potent mammalian collagenase has been implicated in various pathophysiological disorders of bone including arthritis." (PMID 26059174, 2015). "Apart from bone resorption, Cathepsin K plays an important role in the immune system as shown by suppression of experimental arthritis through its pharmacological inhibition." (PMID 30804932, 2019). "In contrast, mRNA expression of TRAP and cathepsin K increased from day 3 and peaked on day 8 after arthritis induction, reflecting increased osteoclastogenesis." (PMID 26801240, 2016). "This was consistent with previous report indicating that inhibition of cathepsin K reduced bone and cartilage degradation evoked by collagen-induced arthritis in mice." (PMID 25374443, 2014). "The findings of the existing trial showed that CFA injections increased the serum levels of MMP-1 and cathepsin K, with a significant concomitant reduction in osteocalcin; these findings concur with other reports of high expressions of MMP-1 and cathepsin K in arthritis." (PMID 36839155, 2023). "Other studies have shown increased MMP-1 and cathepsin K expression in arthritis." (PMID 36839155, 2023). "Moreover, in M3R−/− mice, gene expression of markers for bone degradation (matrix metalloproteinase 13, cathepsin K and receptor activator of nuclear factor-κB ligand) was already increased in mice with low arthritis score." (PMID 26785775, 2016). "This note is corroborated by our observations that NA inhibitory effects on cathepsin K activity were only apparent in CIA osteoclasts with 10-6M being effective before arthritis onset until acute disease state and 10-8M affecting osteoclasts derived from acutely arthritic rats." (PMID 26431344, 2015). "Additionally to MMP13, mRNA expression of cathepsin K and RANKL was already strongly increased in M3R-deficient paws with low arthritis score, while in WT animals enhanced expression was only observed in paws with high arthritis score." (PMID 26785775, 2016). "However, the mild pannus formation and cartilage destruction observed in the MMP-13–/– mice might be due to compensation by other proteases such as cathepsin K, which have been shown to be involved in joint destruction in the collagen-induced arthritis model." (PMID 24369907, 2013). "Uncontrolled osteolysis of the bone tissue is a typical symptom of arthritis, and osteoclasts secrete TRAP and CtsK to induce bone resorption, exacerbating RA symptoms." (PMID 39083495, 2024). "In our study, we observed that DHA effectively reduced arthritis scores and joint swelling, and effectively inhibited the secretion of cytokines IL-17, MMP9, TRAP, and CTSK." (PMID 39257420, 2024). "In summary, inhibition of cathepsin K by ONO-5334 inhibited joint space narrowing, bone atrophy, bone erosion, and architectural joint destruction in this cynomolgus monkey arthritis model." (PMID 30906325, 2019). "Dissection of specific arthritis time-points highlights, that 10-9M VIP mainly inhibited CIA osteoclast cathepsin K activity 15 and 20 days p.i. and, slightly delayed, 20 and 40 days post NaCl-treatment." (PMID 26431344, 2015). "Constitutively overexpressed cathepsin K in mice leads to marked proliferative synovitis and destruction of articular cartilage and bone, and MMP-9 gene deletion mice are significantly less vulnerable to arthritis in mice experiment." (PMID 28463993, 2017). "The overexpression of cathepsin K as shown in RA and collagen-induced arthritis of mice could not be confirmed in AIA at the mRNA level." (PMID 15642138, 2005).